ULBP1 (UL16 binding protein 1)
Diseases named in the same sentence as ULBP1 in open-access papers (continued):
Sharing a sentence is not in itself a finding about the gene and the disease.
tumor (continued). "After mining through the database, it was found that ULBP1 was highly expressed in the majority of tumors (including COAD), compared with adjacent tumor tissues." (PMID 35211154, 2022). "Considering the potential impact of intrinsic NK-92-mediated tumor cell lysis, the NKG2D ligands MHC class I chain-related proteins A and B (MIC-A/-B) and UL16 binding protein 1 (ULBP-1) were assessed." (PMID 33809981, 2021). "Our differential expression analysis results showed that ULBP1, ULBP2, ULBP3, and RAET1L had significant differential expression in COAD tumor and adjacent normal tissues." (PMID 33909599, 2021). "Colocalized analysis showed that the number of ULBP1+CK18+ cells was far greater than that of ULBP1+CD56+ cells in tumor or peritumor tissues, and ULBP1+CK18+ cells had a remarkable enrichment in tumor tissues, indicating that ULBP1 was mainly located in TC." (PMID 34568062, 2021). "NKG2D is an important activating NKR which mainly recognizes stress-induced ULBP1-6 and MICA/B ligands on tumor or virally infected cells." (PMID 32153568, 2020). "In a mouse model, we have observed activation of ULBP1, IL-15, Killer/DR5 and Fas/Apo1 in B16 tumor cells specifically in response to combined p19Arf+mIFNβ gene transfer." (PMID 33193370, 2020). "Gefitinib can upregulate the expression of ULBP1, ULBP2, and MICA in tumor cells and can promote the expression of NKG2D in NK cells, thereby inhibiting tumor escape." (PMID 30813924, 2019). "On the other hand, shed MULT1, a murine ULBP1 ortholog with high affinity for NKG2D, competed with tumor-bound ligands for receptor engagement, thus reversing NKG2D desensitization and promoting tumor rejection in a mouse model." (PMID 31514330, 2019). "These NKG2DLs on tumor cells include MHC class I-related chains A and B (MICA and MICB) and proteins in the UL16-binding protein family (ULBP1-6, mainly ULPBP1–3)." (PMID 29910819, 2018). "Using a forward genetic screen in a tumor-derived human cell line, we identified several novel factors supporting expression of the NKG2D ligand ULBP1." (PMID 26565589, 2015). "Activating signals are delivered by stress-induced ligands, expressed by the tumor itself, such as the MHC class I chain-related gene A and B (MIC A/B) and UL16-binding proteins (ULBP1-6)." (PMID 25854581, 2015). "NKG2D ligands, ULBP1, ULBP2, MICA, and MHC-I on tumor cells, and NKG2D, NKp44 and NKp46 on NK cells were evaluated with flow cytometry." (PMID 23937717, 2013). "Our present study and those of others showed that geftinib can partially up-regulate NKG2D ligands ULBP1, ULBP2 or MICA on tumor cells." (PMID 23937717, 2013). "Formalin-fixed paraffin-embedded tumor tissue was immunohistochemically stained with antibodies directed against MIC-A/MIC-B (MIC-AB), ULBP-1, ULBP-2, ULBP-3, ULBP-4, and ULBP-5." (PMID 22257486, 2012). "Notably, ULBP1 is an immune system-activating receptor on natural killer cells and T cells, and EPHB6 has been shown to suppress tumor invasion and metastasis." (PMID 40837413, 2025). "The increased levels of MICA and ULBP1 bound to NKG2D on NK cells and could lead to NK‐cell exhaustion before the appearance of tumor cells, and the increase in HLAE levels inhibited NKA by binding to NKG2A." (PMID 36931723, 2023). "Vδ2+ T cells are activated by cells that accumulate HMBPP and/or IPP and can also be stimulated through receptors NKG2D and DNAM-1 of various stress-induced molecules expressed on tumor cells including MICA/B, UL16-binding proteins (ULBP1–6), Nectin-2, and PVR, respectively." (PMID 36851283, 2023).
tumor (continued). "Global gene expression analysis of BVE-Ctnnb1null tumor cells showed up-regulation of NKG2D receptor activating ligands (H60a, H60b, H60c, Raet1a, Raet1b, Raet1c, Raet1d, Raet1e, and Ulbp1) and down-regulation of inhibitory MHC class I molecules H-2L and H-2K2 in BVE-Ctnnb1null tumor cells." (PMID 37483610, 2023). "The expression of NK ligands (CD155, CD112, MICA/B, and ULBP1) on single tumor cells in the s.c model did not vary among the control, NK-IVlow, Bev plus Irihigh, and NK-IVlow combined with Bev plus Irihigh groups." (PMID 36703992, 2022). "Further analysis revealed that the high PD-L1 group in tumor tissues had more ULBP1+ cells than the low PD-L1 group (p < 0.05), while no significant change was observed in peritumor tissues." (PMID 34568062, 2021). "In addition, the ligands for activating NK cells, ULBP1 and ULBP3, which play an importing role in the NK-mediated immune response to tumor regression, were also upregulated in the arginine-free diet treated tumors." (PMID 34158865, 2021). "Hsa_circ_0085154 could enhance the innate immune monitoring effect of NK cells by up-regulating UL16 binding protein 1 (ULBP1), which suggests that circRNA may play a role in tumor immunity." (PMID 33614486, 2020). "Gefitinib could block the immune escape by up-regulating the expression of NKG2D ligands ULBP1, ULBP2 or MICA on tumor cells and NKG2D on NK cells in the co-culture system." (PMID 23937717, 2013). "Similar to MIC-A/-B and ULBP1-3 membrane Hsp70 also serves as recognition structure for NK cells that have been activated by the Hsp70 peptide TKD plus IL-2 (TKD/IL-2), both on tumor cells in vitro and in tumor mouse models." (PMID 21179573, 2010). "The MIC gene products and ULBP1-3 proteins act as activating ligands for the C-type lectin receptor NKG2D which is expressed on NK cells and via which activated NK cells can specifically kill their tumor target cells." (PMID 21179573, 2010). "BVE-Ctnnb1null cells showed up-regulation of NKG2D activating ligands (H60a, H60b, H60c, Raet1a, Raet1b, Raet1c, Raet1d, Raet1e and Ulbp1) and down-regulation of inhibitory MHC class I molecules (H2-L, H2-K2, and H2-D1), which may lead to NK cell activation and tumor cell clearance." (PMID 37483610, 2023). "In addition to PD-L1 upregulation, suppression of NK group 2D (NKG2D)-activating ligands (including ULBP1, ULBP2, ULBP3, MHC class I chain-related molecules A and B, MICA and MICB) may represent another way of tumor escape from NKCC." (PMID 34830209, 2021). "However, it is still not clear what drives tumor cells to produce ULBP1 (or other molecules) that are recognized by natural killer cell receptors." (PMID 26565589, 2015). "To explore this hypothesis, we investigated the expression of MICA/B, ULBP1, ULBP2, ULBP3, RAET1E, and RAET1G in normal cervical epithelium and cervical neoplasia in a large series of formalin-fixed, paraffin-embedded tumor samples made by using high-throughput tissue microarray (TMA) technology." (PMID 25510288, 2014). "The metastatic tumor model displayed a greater loss of stress ligands (ULBP1, MICA), downregulation of chemokine expression (MCP-1), and higher production of inhibitory soluble molecules (i.e., TGF-β, IL-6), as compared with a non-metastatic tumor model, more resembling the in vivo scenario." (PMID 35205760, 2022).
tumor (continued). "MICA/B and ULBP4 were moderately (IHC score: 4–6) or highly (IHC score: 7–12) expressed in more than 2/3 HCC tumor samples, whereas ULBP1, ULBP3, and UBP2/5/6 were not (IHC score: 0) or lowly (IHC score: 1–3) expressed in more than 2/3 HCC tumor samples." (PMID 36210637, 2023). "This led to the selection of seven antigens found to be overexpressed in both mouse MM tumor lines under investigation and that were nearly absent in all other mouse normal tissues: KIF20A, KIF2C, MMP9, MNDA, OLFML2B, TROAP, and ULBP1." (PMID 31428586, 2019). "Here we show, for the first time, that human tumor cells lost their surface expression of ULBP2, but not ULBP1 and ULBP3, during NK cell-mediated cytolysis." (PMID 24614922, 2014). "ULBP1 was positively correlated with PD-L1 and CD56 in tumor tissues but not in peritumor tissues." (PMID 34568062, 2021). "Our data also indicate that in contrast to other NKG2DL such as MICA, MICB, and ULBP1–3, which are frequently expressed on a broad variety of human tumor cell lines, ULBP4 may be not or only sparsely expressed on the surface of human tumor cell lines." (PMID 29651291, 2018).
cancer (38 papers, 2014 to 2025). A tumor composed of atypical neoplastic, often pleomorphic cells that invade other tissues. "Among the immunostimulatory factors, IL6R, TNFRSF18, TNFRSF25, and ULBP1 were significantly associated with RCC2 expression in the majority of cancer types." (PMID 36441563, 2022). "For instance, in HCC, circARSP91 was shown to upregulate the expression of UL16-binding protein-1 (ULBP1), a killer cell lectin, to increase the susceptibility of cancer cells to NK cell cytotoxicity, thus enhancing the cytotoxicity of NK cells and promoting immune surveillance." (PMID 33710802, 2021). "In this context, we analyzed the prognostic relationship between the expression levels of KLRK1 and ULBP1-3 in tonsil cancers." (PMID 37565867, 2023). "At the same time, we found that patients with high expression of ULBP2/3 in tonisil cancer had a poor prognosis, whereas high expression of ULBP1 was unrelated to prognosis." (PMID 37565867, 2023). "In other words, we can take advantage of this high expression characteristic in cancer tissues, and the immune-related ULBP1 can better distinguish cancer tissues from normal tissues." (PMID 35211154, 2022). "The mechanisms employed for evading immune surveillance by cancer cells include among others down regulation of surface expression of NKG2D ligands ULBP1, ULPB2 and MICA." (PMID 32592353, 2020). "This cancer cell line constitutively expresses ULBP1 and after treatment with a retroviral promoter trap vector, which randomly knocks out genes, the cell lines that had significant downregulation of ULBP1 surface expression were screened for gene enrichment." (PMID 29973929, 2018). "One called ATF4, which had previously been linked to stress responses, was shown to increase the expression of the gene for ULBP1 in cancer cells." (PMID 26565589, 2015). "This suggests that the variants present in the associated signals may alter not only RAET1L expression but also ULBP1, ULBP2, and ULBP3 and affect the risk of cancer and immune diseases." (PMID 40116579, 2025). "Firstly, this study only investigated the role of KLRK1 and ULBP1-3 inHNSCC, and other types of cancers may have different immune escape mechanisms." (PMID 37565867, 2023). "Additionally, two immunostimulators were associated with ZNF714 expression in a pan-cancer manner, namely, Tumor Necrosis Factor Superfamily Member 15 (TNFSF15) and UL16 Binding Protein, a ligand activating NK and T cells (ULBP1)." (PMID 37958512, 2023). "The transcription factor ATF4 drives the expression of ULBP1 gene in cancer cells, while the RNA binding protein RBM4 supports the expression of ULBP1 by inhibiting a new alternative splicing subtype of ULBP1 mRNA, and explains its mechanism of activating the body’s immune system." (PMID 35211154, 2022). "Meanwhile, very few cancer tissues expressed ULBP1 and ULBP3." (PMID 31288857, 2019). "Additionally, soluble ULBP1 is produced when HCC occurs but not when other cancers metastasize to the liver, indicating its diagnostic specificity." (PMID 39866909, 2024). "In addition, CCNA2 could positively regulate TAP1, TAP2, CD276, MICB, PVR, and ULBP1 in almost all the cancer types." (PMID 35401923, 2022). "NKG2DLs are upregulated in various cancers: MICA in breast, lung, and ovarian cancers, ULBP1–5 in breast cancer, and ULBP6/2/5 in lung cancer." (PMID 40116579, 2025). "The ligands that bind to the NK-activating receptor NKG2D are ULBP1 and ULBP2/5/6, expressed at higher levels in cancer cells than in normal cells." (PMID 41050660, 2025). "For immunomodulators, we found that the KIFscore was positively correlated with ULBP1, MICB, and CD276, while it was negatively correlated with TNFSF13 and TNFRSF14 in the vast majority of cancers." (PMID 37711200, 2023).
cancer (continued). "The authors showed that ULBP1, one of the important ligands of NKG2D, is up-regulated in COAD cancer tissues, but is low-expressed in normal adjacent tissues." (PMID 35211154, 2022). "This exosome-mediated immunosuppressive phenotype has also been observed in prostate cancer cells where cancer cell-derived exosomes containing MICA/B, ULBP1, or ULBP2 led to the downregulation of NKG2D receptor expression on effector populations." (PMID 35565467, 2022). "The ULBP1 (UL16 binding protein 1), known as a “stress-induced ligand”, was upregulated in cancer cells and related to the function of escaping immune surveillance." (PMID 33238517, 2020). "In contrast to this study in human cancer cell lines, we have identified CHOP as a transcription factor that binds the promoter of the mouse ortholog of ULBP1, MULT1, using chromatin immunoprecipitation and luciferase assays." (PMID 29973929, 2018). "Following selinexor incubation, we observed no significant change in the surface expression of ULBP-1, ULBP-2/5/6, MIC-A/B, CD54 (ICAM-1), B7-H6, or externalised calreticulin (ecto-reticulin), recently identified as the cancer associated ligand for NKp46." (PMID 37528310, 2023). "MICB and ULBP1, as NKG2D ligands, have been shown to be potential loci for targeted cancer therapy." (PMID 37225919, 2023). "In terms of immune-activated genes, AURKA exhibited positive correlations with MICB, PVR, CD276, and ULBP1 and negative correlations with C10orf54 in most cancers." (PMID 37965456, 2023). "Although most previous studies reported that ULBP1 was related to recurrence-free survival, disease-free survival, or overall survival (OS) in different cancers, the relationship between ULBP1 and OS in COAD has not been reported yet." (PMID 35211154, 2022). "Deeper investigation of selected hits from the screen showed that the transcription factor ATF4 drives ULBP1 gene expression in cancer cell lines, while the RNA-binding protein RBM4 supports ULBP1 expression by suppressing a novel alternatively spliced isoform of ULBP1 mRNA." (PMID 26565589, 2015). "Therefore, our study uncovers and investigates the diagnosis, prognosis, and immune mechanism of ULBP1 gene in COAD, which may help make this immune receptor an exceptional candidate for basic and applied cancer research in COAD." (PMID 35211154, 2022). "The analysis of 46 immunostimulatory genes in pan-cancer showed that HSP90B1 expression was positively correlated with CD40, CD270, PVR, MICB, ULBP1, TNFSF4, while exhibiting a negative correlation with CD48 and CD40LG in most cancers." (PMID 38243263, 2024). "MICB, ULBP-1, and ULBP-2, but not MICA and ULBP-3, were detected in sera from most patients starting HD, and it was difficult to discriminate between the presence and absence of a cancer history using the levels of soluble NKG2DLs." (PMID 37674990, 2022).
infection (21 papers, 2012 to 2025). The state of being infected such as from the introduction of a foreign agent such as serum, vaccine, antigenic substance or organism. "Moreover, the increase of NKG2D expression may help to protect the fetus against pathogenic infections, since the NKG2D ligands, MICA/B and ULBP1-5, are mainly induced by cellular stresses such as cell damage or pathogen infection." (PMID 22242197, 2012). "In particular, CMVs avoid expression of stress‐ or infection‐induced ligands for activating NK cell receptors on the surface of infected cells, especially the ligands ULBP1, ULBP2, MICA, and MICB for the human activating NKG2D receptor." (PMID 39931744, 2025). "Due to the deletion of the UL16 ORF in the ULBP2‐expressing mutants, induction of other NKG2D‐L was expected upon infection, and, hence, slightly increased ULBP1 expression was observed in HFF infected with ULBP2‐W and ULBP2‐S variants." (PMID 39931744, 2025). "In the infected cells, we observed a 37% decrease in ULBP1 staining after infection compared to the mock-infected controls." (PMID 38953028, 2024). "Next, we evaluated the expression levels of the NKG2D ligands MICA, MICB and ULBP1-3 at 48 hrs post-infection." (PMID 37753084, 2023). "The induction of ULBP-1 occurred 24 h after infection, although it tended to decrease 6 and 12 h after infection." (PMID 33924622, 2021). "As MICB, ULBP1 and ULBP3 are downregulated following infection, we aimed to see if infected cells are less susceptible to NKG2D-dependent recognition by NK cells." (PMID 34721381, 2021). "Host cells, on the other hand, try to prevent further infection by reinforcing tight junctions with neighboring cells and increasing their cell-surface expression of ULBP-1 to inform surrounding cells that they are infected." (PMID 33924622, 2021). "We confirmed that infection of HepG2-NTCP with HBV cells substantially increased the expression of ULBP1 and ULBP2 mRNA in co-cultured THP-1 macrophages, which was cultured using transwell co-culture system." (PMID 27630638, 2016). "In contrast, at 72 hours post infection, the mRNA levels of ULBP1 were substantially reduced, while the ULBP2 and ULBP3 mRNA levels remained unchanged." (PMID 26992229, 2016). "Thus, our finding that U20 inhibits NK cell activation by blocking NKG2D-mediated recognition of ULBP1 represents just a first step in understanding how HHV-6B modulates NK cell responses to facilitate lifelong infection." (PMID 38953028, 2024). "However, ULBP1 levels were twice as high 4 days after infection with ΔEBNA1-EBV as in cells infected with wt-EBV." (PMID 34781735, 2021). "Importantly, in presence of sgRNAs targeting U20, ULBP1 levels were significantly restored after infection and in presence of sgRNAs targeting U21, ULBP3 levels." (PMID 34721381, 2021). "The protein level of ULBP-1 also increased with infection by 1 × 108 CFU/mL of S. aureus." (PMID 33924622, 2021). "Since the ULBP1 reduction occurs late during infection, we considered the possibility that one of the late SV40 proteins might be responsible for the ULBP1 downregulation." (PMID 26992229, 2016). "To characterize the mechanisms leading to ULBP1 downregulation, we first tested, using qRT-PCR, whether ULBP1 mRNA is reduced following infection." (PMID 26992229, 2016). "Interestingly, cell-surface expression of ULBP1 and -2 rose late in infection, suggesting that UL16 had become overwhelmed." (PMID 24906157, 2014). "Thus, we speculate that the infected cells respond to the infection by sensing the L-Tag, via a yet unknown mechanism, by the upregulation of ULBP1." (PMID 26992229, 2016). "Next, we tested whether the total levels of ULBP1 protein are reduced following infection." (PMID 26992229, 2016). "Flow cytometry analysis revealed that Bacilli infection led to a 62% reduction in mean fluorescence intensity (MFI) of the NKG2D ligand MICA/B and a 47% decrease in ULBP1/2 expression on the surface of Huh7 cells." (PMID 40693141, 2025).